YTHDF1 (YTH N6-methyladenosine RNA binding protein F1)
Diseases named in the same sentence as YTHDF1 in open-access papers (continued):
Sharing a sentence is not in itself a finding about the gene and the disease.
tumor (continued). "The inhibition of YTHDF1 results in the overexpression of the interferon‐gamma (IFN‐γ) receptor and activation of the JAK/STAT1 signaling pathways, which increase tumor cells’ sensitivity to the immune response." (PMID 39802639, 2025). "Most regulators, such as METTL3, YTHDF1, IGF2BP3, and RBMX, were upregulated in tumor tissues, while METTL14 and ZC3H13 were downregulated." (PMID 40916616, 2025). "METTL3 is overexpressed in GC tissues, enhancing FNTA translation through YTHDF1-dependent m6A modifications, maintaining KRAS membrane localization and continuously activating the MEK/ERK pathway, driving tumor progression and metastasis." (PMID 41584846, 2025). "Reader m6A proteins, including YTHDF1-3 and IGF2BP1-3, are further strongly involved in HCC pathogenesis by regulating the stability, mRNA translation, and modulating tumor immune microenvironment." (PMID 41157107, 2025). "The results indicated that YTHDF1 and IGF2BP3-dependent m6A methylation positively regulates glycolysis in cancer cells, thereby promoting tumor growth and progress by enhancing the stability and translation efficiency of PDK4 mRNA." (PMID 39904996, 2025). "Dual targeted NP delivery of siRNA targeting YTH N6-methyladenosine RNA binding protein 1 (YTHDF1) to inhibit excessive antigen degradation in DC and tumor cells." (PMID 40061211, 2025). "YTHDF1 enhances NPC cell proliferation, migration, and invasion in vitro and promotes subcutaneous tumor growth and lung metastasis in vivo, which is consistent with its oncogenic role in other malignancies but extends this role to NPC." (PMID 41167308, 2025). "Concurrently, inhibition of YTHDF1 and YTHDF3 in BC cells decreased tumor progression and metastatic capacity by metabolic impairment, reducing PKM2 activity and EGFR modulation accordingly." (PMID 41157107, 2025). "Western blot analysis confirmed that SAC suppressed YTHDF1 and downstream NOTCH1 expression in tumor tissues." (PMID 41423446, 2025). "YTHDF1 overexpression in CSC28 and LS174TS cells increased the tumor-initiating potential and increased the stem cell frequency compared with those of the controls." (PMID 41423446, 2025). "Western blotting confirmed successful YTHDF1 knockdown and consequent NOTCH1 downregulation in tumor tissues following VNP-siYTHDF1 treatment." (PMID 41423446, 2025). "YTHDF1 inhibits CD8+ T cell cytotoxicity by inducing IL‐6 secretion, allowing tumor cells to evade immune surveillance and inhibiting programmed cell death." (PMID 39802639, 2025). "IHC staining of xenograft tumor tissues revealed decreased RNF7 and increased p27 levels in YTHDF1 knockdown groups compared to controls." (PMID 40251202, 2025). "Extensive studies have reported on the roles and mechanisms of YTHDF1 and YTHDF2 in tumor immune regulation." (PMID 41403953, 2025). "Functional assays demonstrate that YTHDF1 enhances NPC proliferation, migration, and invasion in vitro, while promoting tumor growth and metastasis in vivo." (PMID 41167308, 2025). "Comprehensive and systematic investigations are required to compare the consequences of YTHDF1-mediated CD40, CD80, TLR and proteases in DCs-mediated T cell activation in tumor microenvironment." (PMID 40734692, 2025). "These tumor-intrinsic and APC-intrinsic datasets are directionally consistent—YTHDF1 acts as a brake on anti-tumor immunity—while revealing pathway differences (lysosome–MHC turnover versus STING erosion) that depend on cell type and stimulus." (PMID 41280938, 2025). "Targeting YTHDF1 significantly reduced the resistance to anti-PD-1 therapy in the MC38 tumor model, leading to better prognosis for tumor-bearing mice." (PMID 39372415, 2024). "We found that YTHDF1 expression was significantly higher in grade I/II and grade III GBC tissues than in para‐tumour tissues." (PMID 38683130, 2024). "Combined targeting of YTHDF1 and anti‐PD‐1 therapy shows promising anti‐tumour effects in CRC, highlighting YTHDF1 as a significant therapeutic target." (PMID 39135292, 2024).
tumor (continued). "If Ythdf1-cKO+IR mice were to produce higher levels of IFN-β and IFN-γ compared with controls, we would expect increased PD-L1 expression in tumor-infiltrating DCs." (PMID 39325547, 2024). "Knockdown of YTHDF1 slows the development of LUAD, but, at the same time, leads to tumor resistance to cisplatin and adaptation to a hypoxic environment." (PMID 39033180, 2024). "YTHDF1/3, for instance, has been shown to promote carcinogenesis, while YTHDF2 has both oncogenic and tumor-suppressing functions." (PMID 39087001, 2024). "In the co-culture of tumor cells with CD8+ T cells, YTHDF1 overexpression promoted the lactate accumulation and attenuated the cytotoxic CD8+ T cell’s killing effect." (PMID 39557826, 2024). "The silencing of METTL3/YTHDF1 inhibit OC progression and mechanistic study reveals that METTL3/YTHDF1 axis enhanced the expression of the tumor-promoting DDR2 to foster the progression of OC." (PMID 38544837, 2024). "The CRISPR-Cas9 system delivered by these BNMs successfully knocked out the YTHDF1 gene in DCs, leading to CD8 + T cell-mediated tumor inhibition in MC38 tumor-bearing mouse models." (PMID 38990415, 2024). "In conjunction with YTH N6-methyladenosine RNA Binding Protein 1 (YTHDF1), METTL3 mediates m6A modification on JAK1 mRNA, enhancing JAK1 and STAT3 expression and promoting tumor immune escape." (PMID 39659524, 2024). "Specifically, the m6A writers METTL3, WTAP, and RBM15B and the m6A readers YTHDF1 and HNRNAPA2B1 showed significant upregulation in the high PCa tumor grades compared to the low tumor grades and adjacent normal tissues." (PMID 38610981, 2024). "Ythdf1 deletion promoted IFN-I production in DCs and enhanced the cross-priming capacity of DCs and CD8+ T cell–mediated tumor killing in murine cancer models following IR." (PMID 39325547, 2024). "Kazuo Tsuchiya's research in NSCLC found that knocking out YTHDF1 and YTHDF2 elevated PD‐L1 expression in tumours and changed several immune‐related genes." (PMID 39135292, 2024). "Hence, YTHDF1 might cause changes in UHRF1 and Ki67 expression in tumour tissues." (PMID 38683130, 2024). "Reduced m6A levels hinder YTHDF1-mediated translation of SPRED2, contributing to tumor growth and metastasis." (PMID 38444581, 2024). "The deletion of METTL3 in macrophages impairs the YTHDF1-mediated translation of SPRED2, which enhances the activation of NF-kB and STAT3 through the ERK pathway, leading to increased tumor growth and metastasis." (PMID 37928272, 2023). "We hypothesized that the tumor-suppressive function of YTHDF1 deficiency is mainly attributed to the induction of antitumor immunity based on the fact that Ythdf1 deficiency inhibited tumor growth in immunocompetent mice but not in immunodeficient mice or in vitro." (PMID 36650153, 2023). "The result indicated that YTH family, especially YTHDF1 and YTHDF2, had the potential of asking as a tumor progressing biomarker." (PMID 37833468, 2023). "Deletion of YTHDF1 in GC cells led to increased DC recruitment and T cell infiltration because of increased levels of IFNγ receptor 1 (IFNGR1) on the surface of tumor cells." (PMID 37485079, 2023). "Here the authors show that tumor intrinsic YTHDF1 promotes tumorigenesis by regulating lysosomal proteolysis of MHC-I and that YTHDF1 targeting boosts anti-tumor immunity and response to immunotherapy in preclinical cancer models." (PMID 36650153, 2023). "Higher level of YTHDF1 was correlated to a better prognostic outcome of NSCLC patients, much more tumor infiltrating lymphocytes (TILs), and decreased level of PD-L1." (PMID 36707507, 2023). "In lung adenocarcinoma, m6A modification promotes YTHDF1-mediated translation of ENO1 and SLC7A11, thereby enhancing tumor glycolysis and ferroptosis." (PMID 36830614, 2023). "By regulating Pten mRNA for m6A modification via a YTHDF1-dependent mechanism, the downregulation of METTL14 in RCC inhibited Pten expression, leading to the progression of tumours through PI3K/AKT signaling." (PMID 37284313, 2023).
tumor (continued). "The expression of YTHDF1 and YTHDF2 is markedly upregulated in tumor tissues of lung cancer series and possesses tumor-promoting activities." (PMID 36999016, 2023). "In ocular melanoma, down-regulated METTL3-mediated m6A modification leads to attenuated YTHDF1-mediated translation of tumor suppressor HINT2, which promotes tumor progression." (PMID 36830614, 2023). "Deletion of YTHDF1 in DCs enhances the ability of DCs to cross-prime CD8+ T cells, which suggests that YTHDF1 reduced the ability of DCs to present tumor neoantigens to T cells." (PMID 37217462, 2023). "The depletion of YTHDF1 will result in the increased infiltration of CD8+ T cells and synergistically inhibit tumor proliferation in conjunction with immune checkpoint PD-1." (PMID 38202722, 2023). "These indicated that YTHDF1 depletion suppressed tumor antigen and MHC-I degradation, ultimately enhancing tumor recognition and restoring tumor immune surveillance." (PMID 36650153, 2023). "Cancer cells cannot proliferate, migrate, or invade in vitro or in vivo if their lncRNA, THOR, is lost, while the m6A readers YTHDF1 and YTHDF2 can regulate THOR, thus inhibiting tumour formation in vivo and in vitro." (PMID 37542290, 2023). "YTHDC1, HNRNPC, HNRNPA2B1, YTHDF1, YTHDF2, and YTHDF3 all showed significantly high expression in ccRCC (all p-values < 0.0001) compared to the average overall gene expression in the tumour tissue." (PMID 36899967, 2023). "Finally, we investigated whether YTHDF1 maintained HPSCC tumor progression via TLR2." (PMID 37612282, 2023). "In bladder cancer, after m6A modification of ITGA6, YTHDF1 cooperated with YTHDF3 to promote the translation of ITGA6 and mediated tumor progression." (PMID 36830614, 2023). "YTHDF1 expression is significantly higher in CRC tissues than in normal tissues, and the YTHDF1 level is positively correlated with the depth of tumor invasion, lymph node metastasis, and clinical stage." (PMID 35155557, 2022). "A recent research revealed that YTHDF1 knockout in mice dampened tumor growth in an inflammatory CRC model, and DNA copy number gain of YTHDF1 is a frequent event in CRC and contributes to its overexpression." (PMID 35795532, 2022). "Compared with the negative control (antgomir-nc + agomir-nc), the treatment with miR-16-5p induced a significant decrease in the expression of YTHDF1 and PKM2 in the tumor tissues." (PMID 35319018, 2022). "YTHDF1 also increased USP14 levels in an m6A-dependent manner, and USP14 overexpression reversed the tumor-suppressive effects elicited by YTHDF1 silencing." (PMID 36497313, 2022). "The METTL3 deficient mice decreases m6A methylation level of SPRED2, which can’t be recognized by YTHDF1, thus the reduction of SPRED2 translation leads to enhance NF-κB activation and promote tumor progression." (PMID 35022030, 2022). "Yellow background indicated the most significant (p < 0.0001) genes up-regulated in tumor tissues, including HNRNPC, YTHDF1, IGF2BP1, YTHDF2, RBM15, and IGF2BP3." (PMID 35581263, 2022). "Correlation analyses of YTHDF1, YTHDF2, and tumor infiltrating lymphocytes (CD4- and CD8-positive T cells and FOP3-positive T regulatory cells (Treg)) were performed on immunohistochemical and gene expression data." (PMID 36479088, 2022). "Mechanistic studies suggested that deletion of METTL3 disrupted YTHDF1-mediated SPRED2 translation, thereby enhancing NF-kB and STAT3 activation via the ERK pathway, leading to tumor progression." (PMID 36035182, 2022). "To further validate the results, we obtained 60 paired tumor tissues and adjacent normal tissues of ESCC, and qRT-PCR was used to determine the expression pattern of METTL3, METTL14, WTAP, FTO, ALKBH5, YTHDF1 and YTHDF2." (PMID 35399719, 2022). "Some m6A regulators are abnormally expressed in OC, such as YTHDF1, YTHDF2, METTL3, ALKBH5 etc., and promote or disrupt the development or maintenance of tumour phenotypes." (PMID 35303965, 2022).
tumor (continued). "The RMPs upregulated in tumours or showing a positive correlation with poor outcomes usually gained more CNVs, such as ADAR, CPSF1, IGF2BP1, and YTHDF1." (PMID 36118888, 2022). "YTHDF1 and METTL3 expression at protein levels were all upregulated in five tumor tissues compared to their paired normal tissues." (PMID 36008805, 2022). "In terms of additional m6A regulators, one study observed that in mice tumors missing YTHDF1, the degree of CD8+ T and NK cell infiltration was increased, enhancing in vivo tumor antigen cross-expression and CD8+ T-cell cross-priming." (PMID 36091006, 2022). "In another study, the reader gene of YTHDF1 experienced significant upregulation in HCC and showed a positive correlation with the pathological tumour stage." (PMID 34647424, 2022). "Knockdown of YTHDF1 inhibited NSCLC cell growth and the formation of xenograft tumor by adjusting the translational efficiency of CDK2, CDK4, and cyclin D1 and also restrained de novo lung adenocarcinoma progression." (PMID 36017491, 2022). "Concomitantly, m6A-seq unraveled that m6A-mediated modification of EGFR mRNA is induced by sublethal heat stress, which in turn promotes its binding with YTHDF1, leading to the upregulation of EGFR translation to promote tumor metastasis." (PMID 35884552, 2022). "Our results showed that SH3TC2 promoted the cell-cycle progression of CRC as well as tumor growth and that SH3TC2 was a new downstream target of the YTHDF1 molecule in CRC." (PMID 36568637, 2022). "The proportion of CD3+ cells in YTN16 tumor and total immune infiltrates (CD45+ cells) were both significantly higher in YTHDF1 knockout tumors as compared with control tumors." (PMID 35193930, 2022). "In this study, we found that the expression of m6A regulators was up-regulated in HCC tissues, and the up-regulated expression of YTHDF1/2, YTHDC1, RBM15 and METTL3 was significantly correlated with the tumour stage of HCC patients." (PMID 36434140, 2022). "After YTHDF1 was knocked down by shRNA in MCF-7 and MDA-MB-231 cells, the proliferation, migration, invasion and EMT of the tumor cells were significantly suppressed, and G0/G1 phase cell cycle arrest occurred." (PMID 35197112, 2022). "The combination of YTHDF1 silencing and EGFR inhibition dramatically inhibited HCC tumor metastasis after inadequate radiofrequency ablation in vivo, suggesting YTHDF1 as a potential therapeutic target for metastatic HCC." (PMID 35884552, 2022). "After knocking down METL14/YTHDF1, the transcription levels of IFN-α, -β and -γ, which are essential for tumor cell suppression and anti-tumor immune stimulation, are downregulated." (PMID 35303965, 2022). "Correlation analyses among YTHDF1, YTHDF2, and tumor infiltrating lymphocytes were performed using the mRNA expression data of TCGA." (PMID 36479088, 2022). "In fact, combining PD-L1 checkpoint blockade with YTHDF1 depletion enhances CD8+ T cell function and consequently slows tumor progression, providing a reference for the development of strategies utilizing m6A inhibitors in conjunction with PD-L1 therapy." (PMID 35794625, 2022). "YTHDF1 cooperates with the METTL3 m6A effects to enhance the stability of c-Myc, therefore knockout METTL3 can inhibit the malignant progression of tumor cells." (PMID 35022030, 2022). "In this study, METTL3/YTHDF1 elevated FRAS1 protein expression, thus accelerating cell proliferation and tumor growth (colony formation)." (PMID 36008805, 2022). "In conclusion, this is the first comprehensive investigation of the relation between YTHDF1 expression and ESCA tumor cell immune infiltration, glycolysis, ferroptosis, and the ceRNA regulatory network." (PMID 35401696, 2022). "YTHDF1, KIAA1429, HNRNPC, and METTL3 were most significantly upregulated in tumor samples, and METTL16 and METTL14 were markedly downregulated." (PMID 34975871, 2021). "Moreover, YTHDF1 could be a novel target for tumor immunotherapy." (PMID 34026603, 2021).
tumor (continued). "The expression of m6A regulators with CNV amplification was significantly increased in CC samples compared to normal control samples, such as HNRNPA2B1, IGF2BP1, KIAA1429, and YTHDF1, while METTL14 and YTHDC2 were markedly decreased in the tumor specimens." (PMID 33500720, 2021). "For example, YTHDF1 promotes the translation of m6A-marked HINT2 mRNA, a tumor suppressor, which inhibits ocular melanoma progression, and YTHDF2 suppresses cell proliferation and growth via destabilizing the EGFR mRNA in hepatocellular carcinoma." (PMID 33922187, 2021). "Our data show that seven m6A regulators (CBLL1, ELAVL1, LRPPRC, RBM15B, YTHDF1, YTHDF2, and ZC3H13) are related to tumorigenesis, tumor microenvironment and tumor prognosis." (PMID 33670062, 2021). "We conducted a series of assays to determine the role of YTHDF1 in HCC, especially in cell proliferation, which is essential to tumor malignant progression." (PMID 34088349, 2021). "The higher expression of YTHDF1, HNRNPC, IGF2BP1, VIRMA, and HNRNPA2B1, the more characteristics of tumor OV stem cells and the lower the tumor OV differentiation." (PMID 34150845, 2021). "All 39 paired samples were used for expression validation of YTHDF1 and YTHDF3, and the results revealed that YTHDF1 and YTHDF3 had higher expression in 32 and 30 tumor samples compared to the corresponding adjacent tissue, respectively." (PMID 34804948, 2021). "Next, Wilcoxon rank-sum test was conducted between tumor and normal tissues using RNA-seq data of TCGA-COAD; the tumor tissues were found to have lower ALKBH5 expression and higher YTHDF1 expression than normal tissues." (PMID 34079761, 2021). "Initial study on melanoma demonstrated that YTHDF1 can promote translation by binding Histidine Triad Nucleotide Binding Protein 2 (HINT2) transcripts, that in turn promotes tumor cell proliferation, inhibits apoptosis and confers a poor prognosis." (PMID 33692959, 2021). "YTHDF1, a “reader” of m6A, impairs the activation of DCs and CD8+ T cells by increasing the translation of lysosomal cathepsins and thus degrading tumor neoantigens." (PMID 34026603, 2021). "This study identified a broad upregulation of these genes in tumor samples as compared to normal tissues, with significant increases in METTL3, METTL14, KIAA1429 (VIRMA), YTHDF1, YTHDF2, ALKBH5, FTO, WTAP, RBM15, and HNRNPC." (PMID 34209046, 2021). "Downregulated FTO expression substantially increases the m6A modifications on MYC, resulting in the binding of YTHDF1 to promote MYC mRNA translation and tumor cell glycolysis and growth." (PMID 33966037, 2021). "Like the m6A writer proteins METTL3 and METTL14, the m6A reader proteins YTHDF1 and YTHDF2 can act as either an oncogene or a tumor suppressor." (PMID 33922187, 2021). "YTHDF1 also increases Wnt/β-catenin signaling and EIF3C-mediated mRNA translation, promoting tumor cell growth in colon cancer and ovarian cancer, respectively." (PMID 33922187, 2021). "In vitro, YTHDF1 and YTHDF2 knockout in cells up-regulated the expression of tumor PD-L1 and changed a variety of immune-related genes." (PMID 35069586, 2021). "Another study has proposed that overexpressed YTHDF1 and YTHDF3 promotes translation of oncogenes in a m6A-dependent manner in BC, resulting in tumor progression and inferior outcomes." (PMID 33692959, 2021). "In terms of mRNA levels, TRMT6, TRMT61A, TRMT61B, TRMT10C, YTHDF1 and YTHDF2 YTHDF3 were overexpressed in tumor sample." (PMID 34777359, 2021). "Specifically, YTHDF1, IGF2BP2, KIAA1429, RBM15, IGF2BP1, ZC3H13, and METTL3 were significantly up-regulated in tumor tissues by unpaired T-tests (P < 0.05), while ALKBH5, YTHDC2, and METTL14 were significantly down-regulated (P < 0.01)." (PMID 34149792, 2021). "YTHDF1 and YTHDC1 followed it, showing subgroup-to-group expression varieties in 21 and 19 tumor types." (PMID 33585244, 2020).